CPT1A (carnitine palmitoyltransferase 1A)
Diseases named in the same sentence as CPT1A in open-access papers (continued):
Sharing a sentence is not in itself a finding about the gene and the disease.
cancer (continued). "In addition, more and more studies have shown that CPT1A can promote the growth and continuous metastasis of cancer cells to distant tissues, and even autophagy through epigenetic modification and exerting regulatory effects on downstream genes." (PMID 39596847, 2024). "Moreover, other studies have shown a close association between Streptococcus and Parvimonas with the production of various SCFAs and bile acids, which differ from the fatty acids metabolized by CPT1A in the mitochondria of various cancers." (PMID 39456670, 2024). "Cu/Zn-SOD overexpression has been linked to the positive regulation of Carnitine Palmitoyltransferase 1A (CPT1A), which may explain its role in promoting cancer cell growth." (PMID 38972297, 2024). "The same study found that CPT1A was able to induce MAVS Cys79-palmitoylation stabilization and activation, whereas chemotherapy targeting CPT1A could significantly enhance the application of epigenetic therapy in the field of cancer." (PMID 39596847, 2024). "Whether CPT1A can promote cancer progression by directly regulating mitochondrial dynamics is still unclear." (PMID 37291333, 2023). "CPT1A inhibitors can lessen the survivability of cancer cells, so CPT1A may be a useful target for cancer therapy." (PMID 37033619, 2023). "Moreover, CPT1A has been shown to be highly expressed in radioresistant cancer cells and can increase the FAO rate, while inhibition of fatty acid synthesis or targeting CPT1A attenuated radioresistance and decreased radiation-mediated ERK activation." (PMID 37491279, 2023). "Further, we also find that the endocrine-resistant cell lines are highly sensitive to CPT1A inhibitor compared with primary cell lines, and endocrine treatment leads to upregulation of CPT1A, implying that cancer cells develop CPT1A-mediated pathway for cellular adaptation to the new environment." (PMID 37207154, 2023). "Indeed, these studies suggest that inhibition of CPT1A reduces proliferation rates, decreases cancer cell chemoresistance, and increases apoptosis." (PMID 37513899, 2023). "Moreover, CPT1A plays a crucial role in radioresistant and chemoresistant phenotypes in diverse cancer types." (PMID 35008958, 2022). "Furthermore, the expression levels of cell proliferation and cytoskeleton-related proteins increased consistently during cancer development, such as ITGA4, DDC, and CPT1A; thus, they are potential diagnostic markers." (PMID 35958927, 2022). "CPT1A-dependant FAO plays an essential role in the cell cycle progression of cancer cells." (PMID 35411000, 2022). "The levels of CPT1A were strongly decreased in the cancer stem-like cells LN-Flu." (PMID 36325358, 2022). "It was reported that FAO is important for vessel sprouting in cancer and CPT1A might play critical roles in the endothelial cell proliferation and pathological angiogenesis." (PMID 36588740, 2022). "Moreover, CPT1A (carnitine palmitoyltransferase 1a), a rate-limiting enzyme of FAO, was shown to regulate cancer-associated lymphangiogenesis and to be associated with the status of LNM." (PMID 35359362, 2022). "Indeed, overexpression of CPT1A in numerous cancers was observed; rather, the expression level of CPT1A was at significantly low level in patients with CRC." (PMID 36295848, 2022). "Consequently, overexpression of Cpt1a increases free fatty acid (FFA) content in these cancer cells." (PMID 34228639, 2021). "More evidence has confirmed that CPT1A might be a promising target to reverse sensitivity to chemotherapy in cancers." (PMID 34213835, 2021). "Recently CPT1A has been considered as a key regulator of cancer metabolism reprogramming." (PMID 33858374, 2021). "It is possible that in low PHD3-expressing cancers, CPT1-A will be more active." (PMID 33291682, 2020).
cancer (continued). "In addition, since FAO and glycolysis are two functionally coupled metabolic processes that can be utilized by cancer cells, we determined if knockdown of CPT1A alters mitochondria-dependent glucose metabolism using Seahorse analysis." (PMID 32913185, 2020). "Secondly, malonyl COA might be compartmentalized to prevent inhibition of CPT1A so that FAO is uninterrupted or rapidly utilized to meet cancer cells’ high demand for energy and/or biomolecules." (PMID 32312965, 2020). "Together, these results suggest that upregulation of CPT1A may provide a necessary mechanism for cancer cells to adapt a fatty acid-enriched microenvironment." (PMID 32913185, 2020). "It is possible that new inhibitors for ATGL could be of therapeutic value for cancers with increased CPT1A activity." (PMID 33218188, 2020). "This suggests that in CRPC tumors, CPT1A activity can rewire metabolism to promote growth and transformation via activation of serine biosynthesis, folate cycle, and glutathione homeostasis, all geared to maintain an adequate redox balance in the cancer cells." (PMID 33218188, 2020). "Besides being a limiting step for fat oxidation and ATP generation, CPT1A is also necessary for generating metabolic intermediates to synthesize macromolecules like lipids and nucleic acids, which are both essential for cancer growth." (PMID 31547059, 2019). "In conclusion, our results show that improved anti-cancer efficacy can be achieved by co-targeting the AR axis and fat oxidation via CPT1A, which may have clinical implications, especially in the mCRPC setting." (PMID 28915573, 2017). "Our results established the oncogenic relevance of CPT1A and a mechanistic link from lipid catabolism to cell cycle regulation, suggesting that CPT1A could be a prognostic biomarker and rational target for therapeutic intervention of cancer." (PMID 26716645, 2016). "Additionally, another important analysis of the stand-up-2-cancer group (SU2C/PCF Dream team) showed CPT1A gene alteration (mainly amplification) in 11% of PCa cases (n = 150)." (PMID 27384557, 2016). "Additionally, CPT1A may facilitate the tolerance of cancer cells to hypoxic environments by enhancing mitochondrial fatty acid oxidation." (PMID 39763022, 2025). "Furthermore, whether targeting CPT1A in MDSCs can promote IKE-induced cancer therapy in the clinical setting should be explored in the future." (PMID 39596904, 2024). "Next, excessive free fatty acids might trigger the activation of CPT1A in cancer cells." (PMID 38693136, 2024). "We hypothesized that CPT1A expression helps cancer cells to endure hypoxic stress." (PMID 34944922, 2021). "In addition, for the first time, we report that CPT1A regulates cell motility in ARMS cancer cells." (PMID 22533991, 2012). "Recent studies have suggested that CPT1A is a critical link in the communication between the adipocyte‐rich TME and cancer cells." (PMID 39763022, 2025). "Conversely, carnitine palmitoyltransferase 1A (CPT1A), a mitochondrial fatty acid transporter, has been demonstrated to suppress ACSL4 expression and protect cancer stem cells from ferroptosis by facilitating fatty acid β-oxidation." (PMID 40868167, 2025). "In summary, the regulation of FAO through the modulation of CPT1A and CPT1B by factors such as lncAKR1C2, HCP5, and NPRA underscores the complexity of metabolic reprogramming in cancer." (PMID 40365984, 2025). "Studies have found that many of the key mediators of FAO, such as CD36, CPT1 (including CPT1A, CPT1B and CPT1C) and CPT2, are overexpressed in a variety of malignant tumors, and FAO has been found to be enhanced in a variety of cancers." (PMID 40514365, 2025). "Recent studies illustrate that desuccinylase (e.g., SIRT5 and SIRT7) and succinyltransferase (e.g., KAT2A, CPT1A, HAT1, and alpha-KGDH) expression and malfunction are strongly related to immune escape of cancer." (PMID 40865948, 2025).
cancer (continued). "Carnitine palmitoyltransferase 1A (CPT1A), an enzyme critical for FAO, is found to be overexpressed in various cancers." (PMID 40365984, 2025). "Some of these genes are involved in metabolic pathways including fatty acid beta-oxidation and calcification (CPT1A and PHOSPHO1) and in some cancers (PRMT1)." (PMID 37793095, 2024). "In turn, T cell-derived IFN-γ induces upregulation of FAO and CPT1A expression in an AMPK-dependent manner, thereby conferring cancer cells immunologically mediated cytolytic killing capacity." (PMID 39596847, 2024). "CPT1A serves as a rate‐limiting enzyme in mitochondrial fatty acid oxidation (FAO) and is a vital component in numerous cancers." (PMID 39679845, 2024). "Both CPT1A and CPT1B isoforms of CPT1 are now known to function as downstream target genes for PPARα regulation in many cancers." (PMID 39596847, 2024). "Recent research has pointed to the crucial role of CPT1A mediating FAO as an essential source of NADH, FADH2 and ATP, providing survival advantage to cancer, as well as being the carbon source for the synthesis of nucleoside metabolic." (PMID 38003694, 2023). "It is interesting to note that while CPT1A and CPT2 are involved in the same metabolic pathway, their levels of expression, such as CPT1A upregulation and CPT2 downregulation, can have opposite effects in different types of cancer." (PMID 37601653, 2023). "Carnitine palmitoyltransferase 1 A (CPT1A) has been reported to be the key enzyme of FAO, and is upregulated in a cancers." (PMID 37903800, 2023). "Carnitine palmitoyltransferase1A (CPT1A) catalyzes the rate-limiting step in FAO, activates FAO, and fuels cancer growth via ATP and NADPH production." (PMID 37063423, 2023). "We did not provide direct in vivo experiment results to uncover the detailed mechanisms of CPT1A, SCD and FASN over-expression stimulating cancer cell proliferation and metastases." (PMID 38003694, 2023). "Although we have not explored the fatty acid synthesis side, the fact that CPT1A expression increases in BE and EAC and subsets of BE are characterized by a FAO phenotype, suggests that CPT1A and FAO are one of the main roads to cancer." (PMID 36233047, 2022). "Gene sets related to cancer metabolism were compared through RNA-sequencing, and it was confirmed that the expression of FAO-related genes, especially CPT1A, was significantly upregulated in GBM." (PMID 36221088, 2022). "Carnitine palmitoyltransferase 1A (CPT1A), the rate-limiting enzyme of mitochondrial fatty acid oxidation (FAO), has emerged as a key molecule in different cancers." (PMID 36233047, 2022). "Triple negative carcinomas, by contrast, showed low expression of PLIN1, CPT-1A and FABP4, and luminal." (PMID 36180554, 2022). "As the key enzyme of the FAO pathway, CPT1A plays a critical role in generating cellular NADPH to eliminate ROS by activating FAO pathway, thus grants the detached cancer cells with ability of anoikis resistance." (PMID 35003369, 2021). "Carnitine palmitoyltransferase 1A (CPT1A), the key enzyme of FAO, is upregulated in various cancers, and it was reported that CPT1A has been considered a promising target for cancer therapy." (PMID 34213835, 2021). "Carnitine palmitoyltransferase 1a(CPT1a), a rate-limiting enzyme of the essential step of FAO, can facilitate cancer metabolic adaptation." (PMID 33926484, 2021). "Indeed, PGC-1α binds to the transcription factor CCAAT/enhancer binding protein β (CEBPB) to stimulate CPT1A transcription, resulting in FAO activation Moreover, the cellular environment can also contribute to lipid metabolism changes associated with treatment resistance in cancer." (PMID 33339398, 2020). "As fatty acid oxidation (FAO) played an important role in lipid metabolism reprogramming in several types of cancer, we also analyzed the levels of critical FAO-related factors, including CPT1A and ACOX1." (PMID 28604762, 2017).
cancer (continued). "Studies have shown that lipid-enriched cancer cells exhibit increased expression of fatty acid oxidation (FAO) enzymes, such as carnitine palmitoyltransferase 1A (CPT1A) and acyl-CoA synthetase long-chain family member 4 (ACSL4), which sustain ATP production and confer resistance to apoptosis." (PMID 40282189, 2025). "Thus, in cancer cells, SLC25A20 has shown potential to inhibit FAO as an independent target of CPT1A, emerging as a promising strategy to inhibit FAO." (PMID 40521210, 2025). "CPT1A is the most widely distributed isoform of the CPT1 family, and its aberrant expression can lead to metabolic disorders and the progression of various cancers." (PMID 40718711, 2025). "Furthermore, over-expression of CPT1A can also promote EMT and cancer cell stemness, leading to the invasion and metastasis of cancer cells." (PMID 40709184, 2025). "Moreover, the overexpression of leucine-rich repeat kinase 2 facilitates β-oxidation in HepG2 cells and positively affects CPT1A at the transcriptional level by activating AMPK and PPARα, driving cancer cell proliferation." (PMID 41219902, 2025). "Cross-cancer comparative analyses further indicate that HCC TANs show unique metabolic programming, characterised by upregulation of glycolytic genes (HK2, PFKP) and fatty acid oxidation genes (carnitine palmitoyltransferase 1A[CPT1A])." (PMID 41451221, 2025). "We hypothesize that the release of the cancer-related active ingredient S1P by LSEC necessitates inhibition of the key molecules PPARα and CPT-1A under mechanical stress, acting as a protective measure to fulfill sphingolipid biosynthesis demands." (PMID 41039598, 2025). "CPT1A, the rate-limiting enzyme in fatty acid oxidation (FAO) that provides an alternative energy source for the survival of cancer cells, plays a crucial role in metabolic adaptation in cancer pathogenesis." (PMID 40896188, 2025). "Moreover, upregulation of CPT1A expression can promote EMT and stemness, leading to the invasive and metastatic capabilities of cancer cells." (PMID 37700339, 2023). "CPT1A, a largely distributed isoform of the CPT family, is highly expressed in many cancers." (PMID 37046804, 2023). "CPT1A, representing the key enzyme of FAO, has emerged as a promising target for cancer therapy." (PMID 34213835, 2021). "Upregulation of CPT1A and increasing FAO in cancer cells confer antiangiogenic drug resistance." (PMID 33528867, 2021). "In fact, methylation status in the CPT1A gene locus significantly correlates with very low density lipoprotein (VLDL) and low density lipoprotein (LDL) lipoprotein profiles, pointing to an epigenetic role of this gene in metabolic dysfunction and cancer." (PMID 31142021, 2019). "Our current data also reveal a potential crosstalk between CPT1A/CPT2-mediated lipid metabolism and ERK1/2-controlled cell proliferation, implicating a cooperative network of mitochondrial FAO in response to radiation in resistant cancer cells." (PMID 31803610, 2019). "Notably, CPT1A functions as a succinyltransferase by binding to S100A10 and promoting its succinylation, which enhances cancer metastasis and invasion." (PMID 30394687, 2019). "In addition to CPT1A, AMPK regulates CPT1C expression to promote tumor growth upon metabolic stress in several types of cancer cells." (PMID 29996946, 2018). "Additionally, another important dataset from the stand-up-2-cancer group (SU2C/PCF Dream team) also shows CPT1A gene altered (mainly amplification) in 11 % of PCa cases (n = 150)." (PMID 28915573, 2017). "HIF1α activity downregulates the expression of carnitine palmitoyltransferase 1A (CPT1A) and medium- and long-chain acyl-CoA dehydrogenases, key enzymes for the import of mitochondrial fatty acids and for the β-oxidation of lipids, thus limiting fatty acid catabolism in cancer cells." (PMID 39284708, 2024).
cancer (continued). "Particularly, it is not clear how CPT1A activity could promote a metabolic environment conducive to cell transformation, cancer progression and drug resistance." (PMID 33218188, 2020). "TNBCs have lower CPT1A expression than non-TNBCs, suggesting that while accelerated fatty acid metabolism is a characteristic feature of non-TNBCs, the malignancy of TNBCs is driven by other mechanisms such as cell migration and cancer stemness." (PMID 31699026, 2019). "Thus, the CPT1A/CPT2-mediated FAO activity may be differently regulated in normal and cancer cells, which warrants further studies." (PMID 31803610, 2019). "Since CPT1A is not an oncogene, but a liver enzyme also abundant in epithelial cancers, finding its role in cancer has not been intuitive, especially since most cancers have a strong dependency on glucose and rely on the Warburg effect." (PMID 31547059, 2019). "However, CPT1A blockade did not reverse growth suppression in cells treated with palmitate and IACS-010759, indicating that other mechanisms must explain why this combination is toxic to cancer cells." (PMID 36044570, 2022).
metabolic disorders (19 papers, 2014 to 2025). "Some genes are highly involved in insulin secretion regulation, in which CPT1A is associated with the risk of metabolic diseases due to carbohydrate and fat intake." (PMID 41007634, 2025). "CPT1A deficiency is a rare metabolic disease that affects fatty acid oxidation (FAO), and in the majority of cases, patients are diagnosed only after the appearance of clinic symptoms." (PMID 34233743, 2021). "They proposed CPT1A as an indicator of increased risk for metabolic disorders." (PMID 41439952, 2025). "Since CPT1A is the rate-limiting enzyme in fatty acid β-oxidation, deficiencies or aberrant regulation of this enzyme can lead to a variety of illnesses, including malignancies and metabolic disorders, making it a promising drug target for treatment." (PMID 40369321, 2025). "The deficiency of CPT1A or abnormal regulation can result in diseases like metabolic disorders." (PMID 38396525, 2024). "CPT1A deficiency is a rare metabolic disorder of FAO caused by functional mutations in the gene." (PMID 26808626, 2016). "Previous studies have evinced that SIRT2 is significantly correlated with CPT1A expression in metabolic diseases and that the in vitro overexpression of ketohexokinase-C (KHK-C) decreases the level of SIRT2 while promoting CPT1A acetylation." (PMID 40606607, 2025). "Moderately increasing the expression or activity of CPT1A can promote FAO and improve a variety of metabolic diseases caused by high fat diet." (PMID 37033619, 2023). "We propose Cpt1a gene expression analysis in PBMC as an early biomarker of metabolic alterations associated with MONW phenotype due to the intake of isocaloric HF diets, as well as a marker of increased risk of metabolic diseases associated with the intake of HF or HP diets." (PMID 27885970, 2016).